SMARCA4 (SWI/SNF related BAF chromatin remodeling complex subunit ATPase 4)
Diseases named in the same sentence as SMARCA4 in open-access papers (continued):
Sharing a sentence is not in itself a finding about the gene and the disease.
lung carcinoma (continued). "Apart from SCCOHT, germline truncating PVs of SMARCA4 have also been associated with undifferentiated uterine sarcomas and a single case of BRG1/SMARCA4-deficient lung carcinoma." (PMID 33532948, 2021). "SMARCA4-dNSCLC is a smoking-associated undifferentiated or dedifferentiated aggressive lung carcinoma." (PMID 34440689, 2021). "SMARCA4, encoding the BRG1 protein, participates in the chromatin remodeling process and DNA repair and is frequently mutated in lung cancer." (PMID 35096557, 2021). "For lung cancer, complete SMARCA4 loss indeed existed in 5% of adenocarcinomas and squamous cell carcinomas." (PMID 33481850, 2021). "We show that SMARCA4/2 deficiency impairs chemotherapy-induced apoptotic responses in ovarian and lung cancers at least in part by altering ER to mitochondria Ca2+ flux." (PMID 34518526, 2021). "A sensitivity to SMARCA2 loss by RNA interference knockdown was observed in SMARCA4-deficient lung cancers, which triggered a phenotypic lethal response." (PMID 33941852, 2021). "Together, our data indicate that SMARCA4/2 loss inhibits chemotherapy-induced apoptotic responses in ovarian and lung cancer cells." (PMID 34518526, 2021). "While we highlight a subset of lung cancer patients with SMARCA4 truncating mutations, almost 60% of SMARCA4 alterations were missense mutations, and NSCLC patients with homozygous point mutations also trend towards reduced OS (HR 1.85, P = 0.09)." (PMID 33144586, 2020). "Most recently, anti-programmed cell death 1 receptor (PD-1) blockade has been effective for SMARCA4-deficient lung cancer and malignant rhabdoid tumor-like tumors." (PMID 31617320, 2019). "Somatic mutations in SMARCA4, the gene encoding BRG1 (henceforth SMARCA4), occur in 31 of the 159 lung cancer-derived cell lines (19%) in the COSMIC database or sequenced by us (authors' unpublished data)." (PMID 28102363, 2017). "Moreover, a comprehensive literature review and genomic analysis of SMARCA4 mutations in lung cancer were also performed." (PMID 41577374, 2026). "The overall mutation rate for SMARCA4 in NSCLC was 9% according to our genetic analysis, with poorly differentiated NSCLC exhibiting an approximately 12% mutation rate, highlighting the importance of vigilance regarding SMARCA4 mutations in lung cancer patients." (PMID 41577374, 2026). "SMARCA4‐deficient tumours such as non‐small cell lung cancer, colorectal cancer, etc." (PMID 41537447, 2026). "Although INI1-deficient lung cancer is rare, the increasing number of reported cases suggests that it may eventually be recognized as a distinct molecular entity, similar to SMARCA4-deficient thoracic tumors." (PMID 40291911, 2025). "Restoration of SMARCA4 was associated with decreased lung cancer cell proliferation, metastasis, and epithelial–mesenchymal transition, an effect attributed to its positive regulatory role in the expression of miR-148b, which inhibits the WNT1/β-catenin signaling pathway." (PMID 39888726, 2025). "However, SMARCA4 mutations can occur in approximately 5–16% of primary lung cancers and in approximately 10–15% of lung adenocarcinomas." (PMID 38374950, 2024). "SMARCA4 mutation was also reported to influence ICB treatment for lung cancer." (PMID 39323009, 2024). "In SMARCA4/A2-deficient lung cancer model, BETi significantly repressed tumor growth." (PMID 38347129, 2024). "Furthermore, preclinical data suggest that SMARCA4-deficient lung cancer cells exhibit enhanced replication stress." (PMID 39697230, 2024). "Additionally, in a lung cancer mouse model, SMARCA4 mutations have induced a high grade of cell dedifferentiation." (PMID 38542211, 2024). "Further data analysis showed that the SMARCA4 harbored potential site-specific mutations in CRC, including R1157W, R1157Q, and R1243Q, which differed from the distribution of SMARCA4 mutations among other high-incidence and high-mortality cancers (lung cancer, liver cancer, and gastric cancer)." (PMID 36922568, 2023).
lung carcinoma (continued). "We evaluated the ability of SBS signature 4 to predict SMARCA4-d in other cancer types and found a significant predictive association in lung cancer, though much lower than for cancers of unknown primary." (PMID 36883553, 2023). "Approximately 10% of non‐small cell lung cancers (NSCLCs) are susceptible to SMARCA4 loss." (PMID 37184108, 2023). "Thus, the detection of a SMARCA4 variant via NGS was useful not only in defining the particular pathological diagnosis but also in providing important clues for the choice of treatment for SMARCA4-deficient lung cancer." (PMID 36371186, 2022). "To more broadly assess cellular activity and determine whether the moderate selectivity in degradation translated to selective effects on cell growth, we profiled a panel of lung cancer models characterized by SMARCA4 mutation status." (PMID 36357397, 2022). "SMARCA4/2 loss in ovarian and lung cancers is associated with chemotherapy resistance." (PMID 34518526, 2021). "MUC16 and SMARCA4 are attractive therapeutic targets in patients at high-risk for recurrence after surgery for early-stage lung cancer and may warrant further investigation." (PMID 34880292, 2021). "Recent studies have found that treatment with immune checkpoint inhibitors is associated with improved outcomes in patients with SMARCA4 mutated, suggesting that SMARCA4 mutated lung cancer may be more sensitive to immunotherapy." (PMID 35096557, 2021). "Despite the poor outcomes associated to co-mutations, SMARCA4-mutant lung cancers are, in general, more sensitive to immunotherapy and may have an advantageous therapeutic option in the future." (PMID 34440689, 2021). "SMARCA4 is the most frequently mutated Snf2-like ATPase in humans, and it has been found to be inactivated or disrupted in many cancers, including breast cancer, lung cancer and colorectal cancer." (PMID 33941852, 2021). "This hypothesis is also supported by recent evidence showing that PFI-3, a selective SMARCA4/2 BRDi, fails to phenocopy the observed SMARCA2-depleted phenotype in SMARCA4-deficient lung cancer cells." (PMID 31000698, 2019). "In addition, ovarian and lung cancers deficient in one SWI/SNF subunit appear sensitive to loss (by RNAi depletion) of the alternative subunit, e.g. SMARCA2 depletion in SMARCA4-deficient lung cancer cells." (PMID 29515757, 2018). "Interestingly, the same patient carried a new missense mutation in the tumor suppressor gene SMARCA4, frequently mutated in lung cancer and small cell ovarian carcinoma." (PMID 25803323, 2015). "Thus, CBP/p300 dual inhibitors could be promising for SMARCA4/SMARCA2-deficient lung cancer and SS18–SSX fusion synovial sarcoma, which are entirely deficient in the cBAF complex." (PMID 39625239, 2025). "However, KRAS-mutant lung cancer was resistant to BETi, and it may limit BETi monotherapy in SMARCA4-UT which is usually accompanied by KRAS mutation." (PMID 38347129, 2024). "Notably, we found that there is a statistically significant anti-correlation between SMARCA4 (BRG1) mRNA expression levels and those of the immunoproteasome encoding genes in lung cancer samples, suggesting that loss of BRG1 leads to upregulation of immunoproteasome gene expression in cancer." (PMID 35365638, 2022). "In vitro and in vivo SMARCA4/A2-deficient ovarian and lung cancer models showed BETi mediated anti-proliferative effects, showing that SMARCA4/A2 (SWI/SNF-related, matrix-associated, actin-dependent regulator of chromatin, subfamily a, member 4/2) may be used as biomarkers for BETi sensitivity." (PMID 35563709, 2022). "In addition to targeting mutations that drive tumour growth, it is theoretically possible to identify acquired vulnerabilities in cells linked to the loss of tumour suppressors such as SMARCA4, one of the more commonly mutated tumour suppressors in lung cancers." (PMID 28102363, 2017).
lung carcinoma (continued). "Typically diagnosed at an advanced stage, SMARCA4‐UT exhibit poor responses to conventional therapies, resulting in significantly worse prognoses compared to other lung cancer types, with a survival time of approximately 4–7 months." (PMID 41577374, 2026). "With a genetic analysis, it revealed that SMARCA4 mutations, primarily located within the SNF2‐related domain and the helicase conserved C‐terminal domain, are relatively common in lung cancer and are associated with a poorer prognosis." (PMID 41577374, 2026). "Significantly lower levels of SMARCA4 were found in lung cancer cell lines compared to normal lung tissues." (PMID 39888726, 2025). "Emerging evidence highlights the role of SMARCA4 in lung cancer maintenance, carcinogenesis, and treatment." (PMID 40661782, 2025). "In lung cancer, mutations in SWI/SNF subunit genes occur in approximately 20% of cases, with SMARCA4, ARID1A, ARID2, and SMARCA2 being the most commonly affected." (PMID 40291911, 2025). "The expression of multiple genes is regulated by SMARCA4, and their transcription is repressed with the inactivation of SMARCA4 in lung cancer." (PMID 39888726, 2025). "Several studies involving clinical cases, cell lines, and animal models of lung cancer indicate a worse prognosis associated with SMARCA2 and SMARCA4 deficiency in the disease." (PMID 39888726, 2025). "Among tumors with SWI/SNF chromatin remodeling abnormalities, loss of SMARCA4 and SMARCA2 protein expression has been shown to be a poor prognostic factor, particularly in lung cancer." (PMID 40866717, 2025). "Since then, several studies involving primary tumors, cell lines, and animal models of lung cancer have shed more light on the role of SMARCA2 and SMARCA4 deficiency in the disease." (PMID 39888726, 2025). "In SMARCA4-mutant lung cancer cells, ROCK inhibition by KD025 (Belumosudil) suppresses both mitochondrial respiration and adaptive increase in glycolysis induced by inhibition of oxidative phosphorylation." (PMID 40182055, 2025). "In lung cancer and other solid tumors, deficiency of key SWI/SNF subunits (such as SMARCA4/BRG1) profoundly reorganizes chromatin architecture and transcriptional circuitry, thereby reshaping cellular sensitivity to multiple anticancer agents." (PMID 41514604, 2025). "Patients with SMARCA4-UT often presented with huge masses in thorax, including mediastinum, lungs or pleura, and clinical manifestations are different from those of lung cancer." (PMID 38347129, 2024). "Upon passing these stringent criteria, we identified 5 genes as potential hits in IACS-10759-treated SMARCA4-mutant lung cancer cells." (PMID 39345502, 2024). "Previously, we and others have identified that SMARCA4-mutant lung cancers are highly dependent on oxidative phosphorylation (OXPHOS)." (PMID 39345502, 2024). "Overall, combinatorial drug screening revealed that pharmacological inhibition with KD025, a ROCK inhibitor, was our most promising therapeutic with IACS-10759 was highly synergistic in all three SMARCA4-mutant lung cancer cell lines." (PMID 39345502, 2024). "Taken together, these data suggest that the potent, synergistic combination of KD025 and IACS-10759 displays features of synthetic lethality that is detrimental to SMARCA4-mutant lung cancer cell survival." (PMID 39345502, 2024). "In this report, we reveal the discovery of ROCK inhibition as synergistic combination partner to OXPHOS inhibition in SMARCA4-mutant lung cancer." (PMID 39345502, 2024). "Previously, we and others have shown that SMARCA4-mutant lung cancers are highly dependent on OXPHOS15,16." (PMID 39345502, 2024). "Focusing on lung cancer biopsy specimens, SMARCA4 levels were also significantly higher in SCLC than in lung adenocarcinoma." (PMID 39080761, 2024).
lung carcinoma (continued). "SMARCA4-mutant lung cancer is one of the worst prognosis subtypes of lung cancer with dismal outcome and poor response to chemotherapy, immunotherapy and even recently approved KRASG12C inhibitors 70–74." (PMID 39345502, 2024). "A recent study by UT MD Anderson Cancer Center found that when KEAP1, SMARCA4, and CDKN2A co-mutate with KRAS-G12C, KRASG12Ci monotherapy is ineffective in treating patients with advanced lung cancer." (PMID 38817907, 2024). "Future work needs to be done to determine if the enhanced effect of our combination regimen is also observed in SMARCA4 wild type lung cancers and other tumor types." (PMID 39345502, 2024). "Recently, multiple studies have confirmed the correlation between SMARCA4 alterations and immunotherapeutic effectiveness in lung cancer, but the conclusions remain controversial." (PMID 39322625, 2024). "In 60% of patients with SMARCA4‐dNSCLC, the lesions were located in the upper lobe of the lung, and 69% of the SMARCA4‐dNSCLC patients had peripheral lung cancer." (PMID 37184108, 2023). "For example, an orally available allosteric inhibitor of both SMARCA2 and SMARCA4 has been discovered and has demonstrated antiproliferative activity in a mouse xenograft model of SMARCA4-mutant lung cancer." (PMID 36418306, 2022). "For example, one of two mutually exclusive ATPase subunits from the mammalian SWI/SNF subfamily, SMARCA4, was proven to be a tumor suppressor in the lung cancer." (PMID 36361605, 2022). "SMARCA4 mutation directly results in the inability of the SWI/SNF complex, promoting early metastasis of lung cancer." (PMID 36424557, 2022). "In lung cancer, SMARCA4 inactivation is the most common alteration within the SWI/SNF complex and has been associated with poor oncologic outcomes." (PMID 34290393, 2021). "Administering the KDM6 inhibitor GSK-J4 to mice orthotopically implanted with SMARCA4-mutant lung cancer cells or primary small cell carcinoma of the ovary, hypercalcaemic type (SCCOHT), had strong anti-tumour effects." (PMID 34262032, 2021). "Another study showed that the reduced expression of SMARCA4 contributes to poor outcomes in lung cancer." (PMID 33107184, 2021). "An allosteric inhibitor of SMARCA2 and SMARCA4 has demonstrated anti-proliferative activity in a mouse xenograft model of SMARCA4-mutant lung cancer." (PMID 34359794, 2021). "The potential of SMARCA4 and its mutually exclusive paralog SMARCA2 as therapeutic target has been already investigated in the case of lung cancer using an allosteric SMARCA4/SMARCA2 inhibitor." (PMID 33572108, 2021). "In lung cancer, SMARCA4 inactivation affects about one-third of non-small cell lung cancers (NSCLCs) and preferentially occurs against a background of wild type MYC (either C, L or N) or of members of the MYC-axis, such as MAX or MGA4–7." (PMID 34262032, 2021). "Inactivating mutations in SMARCA4 and concurrent epigenetic silencing of SMARCA2 characterize subsets of ovarian and lung cancers." (PMID 34518526, 2021). "As a result, SMARCA4-DTSs were found to be genetically different from lung carcinomas while they displayed a closer molecular relationship to SCCOHT and MRTs." (PMID 33866513, 2021). "SMARCA4 inactivation was shown to promote NSCLC aggressiveness by altering chromatin organization, and the reduced expression of SMARCA4 contributes to poor outcomes in lung cancer." (PMID 33107184, 2021).
lung carcinoma (continued). "In summary, we have uncovered that SMARCA4/2 loss restricts IP3R3-mediated Ca2+ flux from the ER to mitochondria, leading to resistance to chemotherapy-induced apoptosis in ovarian and lung cancers." (PMID 34518526, 2021). "In fact, in cancers such as prostate cancer, colon cancer, and lung cancer, SMARCA4 is an epigenetic regulator and has been reported to promote metastasis through cancer migration and invasion." (PMID 34083693, 2021). "Another study indicated that decreased expression of SMARCA4 resulted in a poor prognosis of lung cancer." (PMID 35070984, 2021). "We studied the differential response to SAHA in lung cancer cells with oncogenic activation of MYC (hereafter referred to as MYCamp) with respect to those with genetic inactivation of SMARCA4 (hereafter, SMARCA4def)." (PMID 34262032, 2021). "In the case of lung cancer, SMARCA4 is the SWI/SNF subunit that displays the highest number of deleterious mutations considering splice-site, stopgain variants, frameshift indels, and large deletions." (PMID 33321963, 2020). "In the case of lung cancer, which is the deadliest type of malignancy worldwide, translational applications have only been developed against SMARCA4-mutant tumors." (PMID 33321963, 2020). "Lung-specific, conditional ablation of Smarca4 enhances tumor formation in a carcinogen-induced lung cancer model." (PMID 31406271, 2019). "It was reported recently that EGFR expression is regulated by SMARCE1, SMARCA4, and ARID1A and that SMARCE1 deficiency confers TKI resistance in lung cancer." (PMID 27783942, 2016). "One recent study showed that miR-155 acted as an oncogene by targeting 3′UTRs of SMARCA4 encoding the SWI/SNF catalytic subunit, and had an association with poor prognosis of lung cancer." (PMID 26543233, 2015). "SMARCA4 is also a known cancer gene, and has been shown to have a role as a tumor suppressor in lung cancer." (PMID 23717195, 2013). "Hence, selective degradation of the SWI/SNF ATPase SMARCA2 by PROTACs YDR1 or YD54 was found to provide better sensitivity in SMARCA4 mutant xenografted lung cancer cells." (PMID 41278204, 2025). "SMARCA4 mutations, reported as the most frequent mutations in the SWI/SNF complex, are associated with poor prognosis in lung cancer, although SMARCA4-mutated lung cancer may be more sensitive to immunotherapy." (PMID 40510148, 2025). "Immunotherapy is now a first-line treatment in the overall management of lung cancer, but the inclusion of immunotherapy and whether it is based on PD-L1 expression in the subgroup of SMARCA4-UT remains inconclusive." (PMID 41142791, 2025). "As studies increasingly correlate SMARCA4 with lung cancer treatment and prognosis, the accurate identification of SMARCA4-deficient tumor subtype becomes critical and may necessitate specific therapeutic strategies." (PMID 40661782, 2025). "In lung cancer, mutations in the SMARCA4 gene account for 12% of non-oncogene-addicted lung adenocarcinomas, while 5% of gene mutations occur concurrently in oncogenic lung adenocarcinomas." (PMID 41142791, 2025). "In lung cancer, SMARCA4 gene mutations account for 12% of non-oncogenic addictive lung adenocarcinomas, with 5% of these mutations also present in oncogenic lung adenocarcinomas." (PMID 41142791, 2025). "The demonstration of a synergistic combination effect of KD025 with OXPHOS inhibitors in OXPHOS-sensitive SMARCA4-mutant lung cancer cells is highly promising and could enable expansion of the therapeutic indications for inhibitors of ROCK and OXPHOS." (PMID 39345502, 2024). "Moreover, a separate subheading focusing on SMARCA4 and KRAS co-mutation survival outcomes in patients with NSCLC is included, as this has recently become a medically relevant topic in the lung cancer community." (PMID 39063938, 2024).